TANC1 (tetratricopeptide repeat, ankyrin repeat and coiled-coil containing 1)
Description:
May be a scaffold component in the postsynaptic density.
Synonyms: KIAA1728; ROLSB; TANC
Tractability: PROTAC: ubiquitination databases record sites on it.
Safety:
Unwanted effects reported when the protein is acted on. In parentheses: how it was acted on, where the effect was seen, and who reports it.
late stage toxicity (source: ClinPGx)
Gene: Protein-coding gene on chromosome 2 (158,968,581 to 159,232,668, forward strand). Ensembl gene ENSG00000115183.
Subcellular location: Postsynaptic density
Gene Ontology:
Molecular function: protein binding
Biological process: regulation of postsynapse organization
Cellular component: glutamatergic synapse; postsynaptic density, intracellular component; axon terminus; dendrite; neuronal cell body; postsynaptic density
Genetic constraint (gnomAD): Loss-of-function variants: 71 observed, 133.54 expected, observed/expected ratio (o/e) 0.53, 90% interval 0.44 to 0.65. The upper end of that interval is the gene's LOEUF score, 0.65, which puts it in group 2 of 6, group 1 being the genes least tolerant of losing a copy. Missense variants: 1,792 observed, 2,192.8 expected, observed/expected ratio (o/e) 0.82, 90% interval 0.79 to 0.85. Synonymous variants: 796 observed, 887.97 expected, observed/expected ratio (o/e) 0.9, 90% interval 0.85 to 0.95.
Homologues: Orthologues: chimpanzee TANC1 (99% identical), macaque TANC1 (97% identical), guinea pig TANC1 (90% identical), mouse Tanc1 (90% identical), rat Tanc1 (89% identical), pig TANC1 (89% identical), rabbit TANC1 (86% identical), tropical clawed frog tanc1 (66% identical), zebrafish tanc1a (56% identical). Paralogues in human: TANC2 (54% identical), CTTNBP2 (12% identical), ANKRD65 (5% identical), ANKRD63 (4% identical).
Diseases named in the same sentence as TANC1 in open-access papers:
TANC1 is named in the same sentence as 17 diseases in open-access papers, as found by Europe PMC text mining. Sharing a sentence is not in itself a finding about the gene and the disease. The quoted sentences say what the papers report.
tuberculosis (2 papers, 2021 to 2024). A chronic, recurrent infection caused by the bacterium Mycobacterium tuberculosis. "Genome-wide association study revealed significant association of TANC1 with sudden cardiac death, and TANC1 hypermethylation was reported in anti-tuberculosis drug-induced liver injury." (PMID 39696495, 2024).
Hepatitis (1 paper, 2021). Inflammation of the liver. "Our results indicated that these genes were significantly enriched in several pathways related to liver metabolism, including liver hyperplasia/hyperproliferation, hepatocellular carcinoma, and liver inflammation/hepatitis, suggesting that the TANC1 gene is related to liver disease." (PMID 34465797, 2021).
Intellectual disability (1 paper, 2016). "Expression levels of the TANC gene family genes TANC1 and TANC2 have been indicated to regulate the density of dendritic spines and excitatory synapses and diagnostic exome sequencing identified a de novo TANC1 missense variation in one patient with severe intellectual disability." (PMID 27774450, 2016).
liver cancer (1 paper, 2022). An epithelial or non-epithelial malignant neoplasm that arises from the liver. "As liver cancer is considered an immunogenic tumor, the relationship between the expression of DOCK2, SCTR, TANC1, ALKBH7, FREM2, and GNG4 and the levels of immune cells and stromal cells was assessed." (PMID 35620462, 2022).
liver disease (1 paper, 2021). "The results showed that these genes were mainly enriched significantly in several pathways related to liver metabolism, suggesting that TANC1 is related to liver disease." (PMID 34465797, 2021).
cancer (1 paper, 2015). A tumor composed of atypical neoplastic, often pleomorphic cells that invade other tissues. "While little is known about TANC1, HSF1 is a heat-shock protein previously reported to be associated with carcinogenesis and poor prognosis, as well as supporting malignancy in a variety of cancers." (PMID 26388441, 2015).
infection (1 paper, 2022). The state of being infected such as from the introduction of a foreign agent such as serum, vaccine, antigenic substance or organism. "It is of note that there were six proteins (Chm, Tgm3, Arhgap24, Tanc1, Agap1, Pnkd) that were uniquely expressed on the third day after infection." (PMID 36061859, 2022).
neurologic disorders (1 paper, 2017). "Recently, investigation of patients with diverse neurologic disorders found TANC1 and TANC2 as possible candidate disease genes." (PMID 28754924, 2017).
TANC1 also shares sentences with these, for which no sentence is quoted: Ataxia (1 paper); colon cancer (1); hepatocellular carcinoma (1); injury (1); liver (1); neurodevelopmental disorder (1); prostate carcinoma (1); sarcopenia (1); tumor (1).